CGAS (cyclic GMP-AMP synthase)
Diseases named in the same sentence as CGAS in open-access papers (continued):
Sharing a sentence is not in itself a finding about the gene and the disease.
cancer (continued). "Binding between cGAS and dsDNA is more likely to occur in “CIN-high” cancers than in “CIN-low” cancers." (PMID 37046775, 2023). "Recent advances in the understanding of the mechanisms of the cGAS/STING pathway have played a major role in advancing and improving cancer immunotherapy." (PMID 37354378, 2023). "cGAS-STING is a powerful cytosolic sensor of double stranded DNA (dsDNA) which has been recently described and is of broad relevance to cancer, aging, and genomic stability." (PMID 37854446, 2023). "The intense study of DNA sensing pathways in the last decade or so has revealed a crucial role of the cGAS–STING–interferon signalling axis in shaping immune responses during infection, autoinflammation and cancer." (PMID 37534795, 2023). "The expression of cGAS and STING has been observed to be significantly reduced in CD8+ T cells derived from cancer patients." (PMID 37153627, 2023). "They showed that CIN induces cGAS-STING which subsequently increases IL-6 expression and activates STAT3 signaling, thereby promoting cancer cell survival and growth." (PMID 36717545, 2023). "As a vital component of host innate immunity, cGAS-STING and its downstream cytokines, especially type I IFNs, link innate and adaptive immunity, making STING an attractive target for cancer immunotherapy." (PMID 37153627, 2023). "Increasing evidence shows that dsDNA mediated activation of cGAS-STING signaling is a vital mechanism in the development of chronic inflammatory diseases, involving in cancer, CVD, and metabolic diseases." (PMID 38152400, 2023). "Although cGAS–STING signalosome is important in the DNA detection of pathogens, it also binds endogenous DNA, which is released from the nucleus of cancer or apoptotic cells." (PMID 37190141, 2023). "The cGAS-STING signaling pathway represents a promising immunotherapeutic target for inflammatory diseases and cancer." (PMID 37920470, 2023). "The cGAS-STING pathway is involved in various pathophysiological processes, including inflammatory responses, cellular senescence, and cancer." (PMID 37658045, 2023). "The increased CCFs in SAHA-treated SCLC cells were related to nuclear porin Tpr, which activated the cGAS-STING pathway, and promoted the secretion of SASP in cancer cells." (PMID 37543653, 2023). "Recent advances in exploring the mechanisms of the cGAS/STING pathway have played a major role in developing and improving cancer immunotherapy." (PMID 37354378, 2023). "The differential expression of cGAS and STING supports our model that cancers produce and secrete cGAMP, which is then detected by surrounding host cells." (PMID 38117852, 2023). "Mechanism study showed that RC48 not only induces cell cycle arrest but also disrupts HER2-mediated restain of cGAS-STING signaling, potentially activating an immune response against the cancer cells." (PMID 37620320, 2023). "The key role of cGAS/STING in immunoregulation distinguishes it as an important target for immunotherapies, especially cancer-related, and is the rationale behind the use of STING agonists as promising vaccine adjuvants." (PMID 37298177, 2023). "Innate immune signaling is triggered by the activation of cGAS-STING, and this promotes adaptive immune responses to help fight cancer." (PMID 37667279, 2023). "In certain models of TNBC cells exhibiting high CIN, a reduction in cGAS–STING levels resulted in decreased IL-6 production and reduced survival of cancer cells." (PMID 38139802, 2023). "A recent study demonstrates that cGAS–STING drives IL-6–STAT3 signaling, which promotes the survival of chromosomally unstable cancers." (PMID 37036972, 2023). "Nevertheless, several lines of evidence also link the cGAS-STING pathway, STAT1 activation and IFN signaling to the upregulation of the expression of the immune checkpoint protein PD-L1 in cancer cells as well in cells of the immune system." (PMID 36960066, 2023).
cancer (continued). "Consistent with this, herein, we show that inhibition of ATM induces the activation of cGAS-STING-IFNβ ubiquitously in multiple human and murine cancer cell lines." (PMID 36778120, 2023). "Interestingly, the downregulation of the cGAS/STING pathway itself was shown to be a predictive biomarker for certain cancer subtypes, opening up the potential to identify patient groups that could benefit from cGAS/STING re-enhancing immunotherapy agents such as ENPP1 or TREX1 inhibitors." (PMID 38022587, 2023). "The cyclic guanosine monophosphate (GMP)-adenosine monophosphate (AMP) synthase (cGAS) and stimulator of interferon genes (STING) (cGAS-STING) signalling pathway has become a prominent subject of interest in cancer immunotherapy." (PMID 37448962, 2023). "When exosomes deliver dsDNA from radiation-damaged cancer cells to DCs, type I interferon (IFN-I) is activated via the cGAS/STING pathway.RT-TEX serve as transmitters of the molecular alterations that occurred in radioactively treated cancer cells." (PMID 37667279, 2023). "The cGAS-STING signaling pathway is a mediator of T-cell activation, trafficking, and cancer cell killing in part through type I IFN production." (PMID 36968140, 2023). "In this scenario, cGAS recognizes the abnormal DNA and swiftly reacts to activate STING, which in turn triggers a cascade reaction that kills cancer cells through an innate immune response." (PMID 37762239, 2023). "The nuclear cGAS then attenuates the DNA damage response (DDR) mediated by homologous recombination, thereby facilitating cancer development in these cells." (PMID 37686127, 2023). "Although cGAS-STING and autophagy have been shown to be interrelated in innate immunity, little has been reported about cancer immunity." (PMID 36936940, 2023). "The last approach uses stimulator of IFN gene (STING) agonists, using the cyclic GMP-AMP synthase (cGAS)-STING pathway for stimulating the adoptive and innate immunity against the cancers." (PMID 37970206, 2023). "Furthermore, cGAS-DNA liquid condensates may represent another barrier to modulating the cellular efficacy of cGAS inhibitors, since liquid-liquid phase separation has been emerging as a novel mechanism of understanding the pharmacodynamics for cancer therapeutics." (PMID 37783727, 2023). "Together, these studies demonstrate the complicated and intertwined relationship between (cGAS)/STING activity and STAT3 signaling in cancers with CIN." (PMID 37561163, 2023). "Similar to cGAS, TLR9 can recognize RNA:DNA hybrids, and activating TLR9 has demonstrated potential as a novel immunotherapeutic approach to improve classic cancer therapies." (PMID 37138342, 2023). "Given the crucial role of cGAS/STING signaling in the induction of anti-cancer immunity, STING agonists hold a promise to enhance the ICB response for treating advanced cancer patients." (PMID 37237031, 2023). "A series of reports, including some from our group, have demonstrated that the cGAS-STING signaling pathway, involved in innate immune sensing of DNA, is severely impaired in HPV+ cancer cells." (PMID 37356050, 2023). "It has been reported that in a wide variety of cancers, STING signaling can be suppressed by epigenetic silencing of cGAS or STING itself." (PMID 37655095, 2023). "Several genotoxic treatments, both in the clinic and in animal models, have been found to up-regulate the cGAS-STING pathway and enhance the efficacy of cancer immunotherapy." (PMID 36831197, 2023). "The cGAS-STING pathway is important for immunity against numerous infections and cancers and has emerged as an attractive target for immunotherapy." (PMID 37937842, 2023).
cancer (continued). "Recent studies have revealed that the innate immune system pathway, cGAS/STING/IRF3, plays a critical role in DNA damage response and immune regulation in various cancers." (PMID 38057852, 2023). "The mitochondrial DNA (mtDNA) activated cyclic guanosine monophosphate–adenosine monophosphate synthase—stimulator of interferon genes (cGAS-STING) signaling pathway is a key player in mediating immune responses in autoimmune disorders and cancer." (PMID 37656236, 2023). "As expected, MTHMS + L treated cancer cells significantly boosted DC maturation, which was driven by the striking IFN-β release after cGAS-STING pathway activation." (PMID 37221157, 2023). "In non-cancer contexts, MALAT1 has been reported to activate cGAS/STING through CREB, therefore promoting inflammatory lung conditions." (PMID 37370745, 2023). "We also discuss cGAS-STING activation in cancer cells and the surrounding normal cells that eventually contribute to cancer progression." (PMID 35741087, 2022). "The cGAS-STING pathway plays an important role in infection, autoimmunity, cancer and neurodegenerative diseases." (PMID 36379959, 2022). "Our findings show that anticancer TOP1 poisons, CPT and LMP776, increase micronuclei generation with a mechanism involving R-loop accumulation, leading to activation of the cGAS-STING pathway and immune gene expression in HeLa cancer cells." (PMID 35794238, 2022). "The presence of cytosolic DNA can trigger activation of the cGAS-STING pathway, an innate antitumor immune response, in SCLC and other cancers." (PMID 35584676, 2022). "Given the important role of cGAS–STING in anticancer immunity, STING agonists have been developed to treat cancer." (PMID 35325182, 2022). "After activation of cGAS and effector STING, cytoplasmic DNA stimulates the secretion of interferon beta by cancer cells." (PMID 36467504, 2022). "The cGAS/STING pathway is a major regulator of DDRi-induced immune stimulation, though the STAT1 pathway, TRAIL pathway, and direct activation of anti-cancer immune cells also play important roles." (PMID 36276148, 2022). "A previous study has suggested that the cGAS-STING signaling pathway is important in regulating inflammatory response and cancer progress." (PMID 35892659, 2022). "Particularly, response to immunotherapy is likely driven by both active cGAS-STING signaling that attracts immune cells, and by the presence of cancer neoantigens that presents as targets for cytotoxic T cells." (PMID 36923311, 2022). "Collectively, our findings suggested that RocA was a potent cGAS-STING agonist and had a potential application in cancer immunotherapy, especially in NK cell-based immunotherapy." (PMID 35002511, 2022). "Drp1 overexpression significantly induces mitochondrial dysfunction and cytosolic mtDNA stress, which subsequently activates the cGAS-STING pathway and triggers autophagy, consequently promotes ESCC cancer growth." (PMID 35209954, 2022). "The cGAS–STING signaling pathway is a key mediator of inflammation and innate immunity in settings of infection, cellular stress, and cancer." (PMID 36221123, 2022). "In contrast to the well-documented antitumor activities induced by the cGAS-STING pathway, we revealed that the majority of cancer types had higher cGAS-STING scores compared with their normal counterparts." (PMID 35983076, 2022). "Taken together, our current findings suggested that RocA was a potent cGAS-STING agonist and had a promising potential in cancer immunotherapy, especially in NK cell-based immunotherapy." (PMID 35002511, 2022). "The cGAS-STING pathway is essential for immune defense against microbial pathogens and malignant cells; as such, STING is an attractive target for cancer immunotherapy." (PMID 36442099, 2022).
cancer (continued). "Despite the various mechanisms that have been reported to prohibit improper cGAS–STING activation by self-dsDNA, in many pathological contexts, including cancer and autoimmune disorders, self-DNA can still activate this pathway." (PMID 35325182, 2022). "Even though further research is needed, previous studies have proposed the association between the telomere maintenance mechanisms and the cGAS-STING pathway, which contributes to cancer development." (PMID 35741087, 2022). "Micronuclear DNA or chromatin bridges were shown to trigger an IFN response in cancer cells treated with genotoxic drugs, and TREX1 was reported to limit cGAS activation in genetically unstable cells by degradation of micronuclear DNA." (PMID 35634291, 2022). "In fact, numerous studies have explored the immunotherapy targeting cGAS-STING signaling pathway, especially in tumor and cancer treatment, showing great therapeutic potential." (PMID 35844623, 2022). "In parallel, RT can also lead to the accumulation of cytosolic micronuclei in cancer cells, which activates type I IFN through the cGAS/STING pathway and increases the infiltration of immune cells." (PMID 36139006, 2022). "A recent review highlighted that vaccines adjuvant with cGAS-STING agonists were found to mediate a robust immune defense against infections and cancer." (PMID 36560581, 2022). "Next, we investigated the role of cGAS-mediated AIS in the local and abscopal anti-cancer efficiencies of radiotherapy." (PMID 36402783, 2022). "In the experimental studies performed on cancer cell lines, it was shown that E7 oncoprotein of HPV16 blocked cGAS-STING response in infected cells." (PMID 36289800, 2022). "For the surveillance function of micronuclei by cGAS, cytoplasmic DNA induced by IR promotes type I IFN production through cGAS–STING pathway in cancer cells and triggers subsequent innate immune signaling." (PMID 35906199, 2022). "The expression of cGAS was found only in cancer cells, whereas STING was found predominantly in cancer cells." (PMID 35773436, 2022). "In summary, the cGAS-STING pathway has great potential in cancer immunotherapy as it improves the immune ability and facilitates the combined cancer biotherapeutic efficacies." (PMID 35889509, 2022). "Recently, a variety of studies have validated that cGAS‐STING pathway played critical roles in type I IFN signalling and anti‐cancer immunity." (PMID 35415876, 2022). "In recent years, there is increasing evidence that the cGAS-STING pathway is closely related to the occurrence, development and regression of cancer." (PMID 36353640, 2022). "At the establishment stage of cancer or in experiments observing short-term outcomes, CIN/aneuploidy mainly induces acute cGAS-STING signaling, which activates the antitumor type I interferon response and SASP." (PMID 36003402, 2022). "Thus, targeting nuclear cGAS may be a useful approach for cancer prevention and therapy." (PMID 34374004, 2022). "The cGAS-STING pathway, which was initially found to function in pathogen detection, has recently been demonstrated to be involved in the inhibition of cancer initiation and progression." (PMID 35978045, 2022). "Several pre-clinical and clinical genotoxic therapies have also been shown to upregulate the cGAS-STING pathway and potentiate cancer immunotherapy in animal models." (PMID 36362142, 2022). "cGAS staining was mainly detected in the cytoplasm of precancerous and cancerous cells, while STING staining was detected in the cytoplasm of cancer cells and stromal cells such as lymphocytes." (PMID 36061145, 2022). "In short, the cGAS/STING pathway plays a critical role in cancer and is a potential pharmacological target for treating cancer patients." (PMID 36387071, 2022). "TLK2 depletion activates the cGAS–STRING–TBK1 innate immune axis, and a high TLK2 level contributes to immune evasion of cancers positive for alternative lengthening of telomeres." (PMID 36134026, 2022).
cancer (continued). "Given the critical role of cGAS-STING pathway in bridging innate and adaptive immunity, STING is the potential target for cancer immunotherapy." (PMID 35062949, 2022). "Mechanistically, cytosolic mtDNA activates the cGAS-STING pathway and facilitates autophagy, which promotes ESCC cancer growth." (PMID 35209954, 2022). "As in the case of SARS-CoV-2, human epithelial cancer cells are also reported to respond to cytosolic RNA via the RIG-I-MAVS-IRF3 pathway and sense cytosolic DNA via the cyclic GMP-AMP synthase (cGAS)-stimulator of interferon genes (STING) pathway." (PMID 36439216, 2022). "The abnormal surrounding cells show characteristics similar to cancer cells, such as genome instability and DDR defects, which activate the cGAS-STING pathway." (PMID 35741087, 2022). "Altogether, the results show that chemically unrelated ligands promote autophagy in cancer cells, likely dependent on the activation of ATM and cGAS/STING pathways." (PMID 36114513, 2022). "ATM inhibition, ATR inhibition, Chk1 inhibition, PARP inhibition, and WEE1 inhibition have all been shown to lead to cGAS-STING pathway activation and potentiation of cancer immunotherapy." (PMID 36362142, 2022). "Since the cGAS-STING pathway has a vital role in immunomodulation against tumorigenesis and cancer development, the activation of STING is expected to be used in cancer immunotherapy." (PMID 35889509, 2022). "There is an innate advantage of the cancer-activated cGAS-STING pathway, for cancer cells share common characteristics, including genomic instability, mutations or deletions of oncogenes, oxidative stress, and exuberant metabolism." (PMID 36231006, 2022). "In this work, we explored the role of the cGAS-STING pathway and cancer-induced CIN in the context of immunotherapy response." (PMID 36923311, 2022). "Their study mainly described the mechanism of cGAS-STING signaling pathway in inflammation and cancer and found that cGAS-STING can mediate not only protective immune defense but also antitumor immunity." (PMID 36467504, 2022). "Another mechanism of synergy between genotoxic cancer therapies and immunotherapy is activation of the cyclic GMP–AMP synthase (cGAS)-stimulator of interferon genes (STING) pathway." (PMID 36362142, 2022). "IRF3 is activated by several innate immune receptors, including the cGAS/STING pathway, a novel immunotherapy target with ongoing clinical trials in cancer." (PMID 36092893, 2022). "Activated cGAS-STING signaling transcriptionally provokes the expression of various cytokines and subsequent recruitment of immune cells to cancer cells." (PMID 35773436, 2022). "In conclusion, the present findings demonstrate that cytostatic doses of two established G4 binders activate a cytoplasmic cGAS- and STING-dependent signaling pathway leading to innate immune gene activation in cancer cells." (PMID 34139015, 2021). "In this review, we focus on the dichotomous roles of cGAS/STING in TME remodeling and its profound influence as a potential therapeutic strategy against cancer." (PMID 35265630, 2021). "In this review, we depict the evolution and the broad biological functions of the cGAS-STING DNA sensing platform in pathogen recognition, immune activation, and cancer development, as well as its potential for the development of novel therapeutic strategies." (PMID 33708225, 2021). "Given how sensitive the cGAS–STING pathway is to abnormal intracellular DNA, researchers are interested in investigating the effects of this pathway on cancer." (PMID 34906241, 2021). "A previous report analyzed the relationship between the mRNA expression of key molecules of the cGAS/STING signaling pathway and OS in various cancer using TCGA data." (PMID 34768716, 2021). "These dsDNA sensed by cGAS trigger the transduction of cGAS/STING signaling pathway, which promotes the activation of CD8 + cytotoxic T cell-mediated destruction of cancer." (PMID 33858512, 2021).